ERH (ERH mRNA splicing and mitosis factor)
Description:
May have a role in the cell cycle.
Synonyms: DROER
Tractability: PROTAC: UniProt records ubiquitination sites on it; ubiquitination databases record sites on it; its protein half-life has been measured.
Gene: Protein-coding gene on chromosome 14 (69,380,123 to 69,398,334, reverse strand). Ensembl gene ENSG00000100632.
Subcellular location: Nucleus
Subcellular location (Human Protein Atlas): Nucleoplasm; Cytosol
Gene Ontology:
Molecular function: methyl-CpG binding; protein binding; RNA binding
Biological process: mRNA export from nucleus; nucleobase-containing compound metabolic process; pyrimidine nucleoside metabolic process
Cellular component: methylosome; midbody; nucleus; transcription export complex
Genetic constraint (gnomAD): Loss-of-function variants: 1 observed, 11.03 expected, observed/expected ratio (o/e) 0.0907, 90% interval 0.031 to 0.43. The upper end of that interval is the gene's LOEUF score, 0.43, which puts it in group 1 of 6, group 1 being the genes least tolerant of losing a copy. Missense variants: 34 observed, 107.96 expected, observed/expected ratio (o/e) 0.31, 90% interval 0.24 to 0.42. Synonymous variants: 36 observed, 39.05 expected, observed/expected ratio (o/e) 0.92, 90% interval 0.71 to 1.22.
Homologues: Orthologues: chimpanzee ERH (100% identical), dog ERH (100% identical), guinea pig ERH (100% identical), macaque ERH (100% identical), mouse Erh (100% identical), mouse Erhrt-ps (100% identical), pig ERH (100% identical), tropical clawed frog erh (99% identical), zebrafish erh (99% identical), Drosophila melanogaster e(r) (76% identical), rat Erhl1 (68% identical), Caenorhabditis elegans erh-1 (54% identical), and 1 more.
Diseases named in the same sentence as ERH in open-access papers:
ERH is named in the same sentence as 26 diseases in open-access papers, as found by Europe PMC text mining. Sharing a sentence is not in itself a finding about the gene and the disease. The quoted sentences say what the papers report.
bladder cancer (7 papers, 2019 to 2022). "There is a lack of research on the molecular interaction of the enhancers of rudimentary homolog (ERH) in bladder cancer (BC) cells." (PMID 35774124, 2022). "Knockdown of ERH inhibits the migration and proliferation of bladder cancer cells and ovarian cancer cells." (PMID 35686107, 2022). "According to our review of relevant previous studies, the ERH gene is more expressed in bladder cancer than in normal bladder tissue, and promotes proliferation as well as inhibits cell death." (PMID 35677162, 2022). "The ERH OE bladder cancer T24 cell line was established by lentiviral transfection." (PMID 35774124, 2022). "Cell line studies show that ERH may regulate proliferation in ovarian cancer and melanoma and regulates migration and invasion in urinary bladder cancer." (PMID 34885095, 2021). "The ERH gene might affect the apoptosis of bladder cancer T24 cells through TLR, NF-κB, TNF, or TGF-β signaling pathways, activating the growth of malignant tumors." (PMID 33552118, 2020). "This may provide a basis for the clinical application of ERH as a target for the detection and treatment of bladder cancer, which has great clinical potential." (PMID 30866868, 2019). "This study further explored the mechanism of the ERH gene in the metastasis of the T24 human bladder cancer cell line and found that ERH may regulate MYC gene expression." (PMID 30866868, 2019). "In addition, low ERH expression is associated with better survival in cancer patients whose cancers harbor KRAS mutations while ERH was reportedly involved in cancer metastasis and EMT of bladder cancer." (PMID 33809701, 2021). "Therefore, targeting the ERH-MYC-EMT regulatory circuit may be a novel strategy for the treatment of bladder cancer." (PMID 30866868, 2019). "Further study showed that ERH can regulate the expression of myelocytomatosis (MYC)gene to have an effect in the migration and invasion of T24 and 5637 bladder cancer cells." (PMID 35677162, 2022). "Therefore, targeting ERH could be considered as a new strategy for bladder cancer treatment." (PMID 35774124, 2022). "They found that ERH gene knockdown suppressed MYC-mediated migration and invasion in bladder cancer T24 cells." (PMID 33552118, 2020).
ovarian carcinoma (6 papers, 2008 to 2023). A malignant neoplasm originating from the surface ovarian epithelium. "Overexpression of ERH in gastric cancer decreases cell migration and invasion and is associated with a good prognosis, while in ovarian cancer, ERH promotes metastasis and invasion by regulating EMT." (PMID 37430270, 2023). "Since similar results were obtained for ovarian cancer, ERH overexpression may be implicated in the initiation and/or progression of certain human malignancies." (PMID 18500978, 2008). "ERH is highly expressed in breast cancer tissues, ovarian cancer tissues, and HCC tissues, and affects both migration and tumorigenicity." (PMID 35686107, 2022). "However, a study of ovarian cancer suggested that ERH may be a associated with a poor prognosis, and inhibiting ERH expression can promote cancer cell apoptosis and inhibit the metastasis and invasion of ovarian cancer cells by regulating the epithelial-mesenchymal transition (EMT)." (PMID 35991559, 2022). "Since similar results were obtained for ovarian cancer, the expression pattern and the prognostic role of ERH in breast cancer and gynecologic malignancies awaits evaluation in future studies." (PMID 18500978, 2008). "They considered that ERH could be used clinically as a prognostic factor in breast and in ovarian cancers." (PMID 35677162, 2022). "A similar expression pattern was also found in ovarian cancer (by MTN), suggesting that ERH overexpression might be implicated in the initiation and/or progression of other human malignancies as well." (PMID 18500978, 2008).
gastric cancer (5 papers, 2021 to 2023). A primary or metastatic malignant neoplasm involving the stomach. "Increased expression of ERH was also detected during erythropoiesis and in various human cancers, including breast, ovarian, liver, bladder, skin and gastric cancers." (PMID 37887293, 2023). "Overexpression of ERH augmented the apoptotic effect of anthocyanins on the gastric cancer cell line." (PMID 37887293, 2023). "The overexpression of ERH weakens the invasion and migration ability of gastric cancer cells, suggesting that it is a prognostic marker." (PMID 35991559, 2022). "Decreased ERH expression also correlated with better survival of gastric cancer patients, albeit not significantly, and another study showed the opposite in the case of patients with this cancer having an elevated level of the ERH protein." (PMID 37887293, 2023). "It has been proven that ERH can combine with Pontin, a highly conserved AAA+ adenosine-triphosphate enzyme (ATPase) family member, to have an effect on serine-phosphorylated STAT3, regulating canonical tyrosine phosphorylation and enhancing transcriptional activity in gastric cancers." (PMID 35677162, 2022).
breast carcinoma (4 papers, 2008 to 2022). "In primary human breast cancer and breast cancer cell models, quantitative RT-PCR found that ERH expression was significantly more upregulated in tumorigenic breast cancer cell lines than in non-tumorigenic cell lines." (PMID 33552118, 2020). "In 2008, it was shown that the expression of ERH is clearly higher in malignant breast cells than in benign breast cells in both primary human breast cancer and cell models of breast cancer." (PMID 30866868, 2019). "ERH was identified by this in silico approach among other genes, and this gave us the impetus to further study its expression in human breast cancer." (PMID 18500978, 2008). "ERH expression was further analyzed by MTN in a set of four matched breast cancer/normal breast tissue samples, and a set of four malignant/normal ovarian tissue samples (Clontech, Heidelberg, Germany)." (PMID 18500978, 2008). "In the present study, the gene expression pattern of ERH has been systematically analyzed in normal human tissues, breast cancer cell lines and a panel of malignant and normal human breast and ovarian tissue samples using three independent methods." (PMID 18500978, 2008). "The aim of the present study was a systematic characterization of ERH expression in human breast cancer in order to evaluate possible clinical applications of this molecule." (PMID 18500978, 2008). "ERH expression is clearly up-regulated in malignant as compared with benign breast cells both in primary human breast cancer and in cell models of breast cancer." (PMID 18500978, 2008). "ERH expression was further analyzed in breast cancer and normal breast tissues and in tumorigenic as well as non-tumorigenic breast cancer cell lines, using quantitative RT-PCR and non-radioisotopic in situ hybridization (ISH)." (PMID 18500978, 2008). "ERH expression was up-regulated in breast cancer as compared with normal breast tissue." (PMID 18500978, 2008). "Further studies on large breast cancer tissue cohorts should determine whether ERH could function as a prognostic factor or even a drug target in the treatment of human breast cancer." (PMID 18500978, 2008). "Interestingly, ERH was very abundantly expressed in the highly metastatic breast cancer cell line BT20." (PMID 18500978, 2008). "The human gene ERH (Enhancer of the Rudimentary gene Homologue) has previously been identified by in silico analysis of four million ESTs as a gene differentially expressed in breast cancer." (PMID 18500978, 2008). "In the present study, we present a systematic expression analysis of ERH in a panel of breast cancer cell lines and malignant and normal human breast tissue samples using Northern blot, quantitative RT-PCR and non-radioisotopic RNA ISH." (PMID 18500978, 2008). "Cellular localization of ERH mRNA in breast cancer and normal breast tissue was analyzed with non-radioactive RNA ISH." (PMID 18500978, 2008). "On the other hand, more abundant ERH expression in tumorigenic as compared with non-tumorigenic breast cancer cell lines and the trend of higher expression in malignant as compared with normal tissue samples suggest that ERH could be possibly used as a prognostic factor in breast cancer." (PMID 18500978, 2008). "In order to investigate the possibility that ERH might be differentially expressed in different stages of mammary tumour progression we have compared ERH mRNA levels in non-tumorigenic (i.e. MCF10A and MCF12A cells) and five different tumorigenic breast cancer cell lines with LightCycler® RT-PCR." (PMID 18500978, 2008).
hepatocellular carcinoma (4 papers, 2008 to 2022). A malignant tumor that arises from hepatocytes. "It was shown that loss of ERH attenuated UV-induced DNA damage repair in hepatocellular carcinoma (HCC) cells." (PMID 35677162, 2022). "The present study investigated the role of ERH and its target DNA damage repair genes in hepatocellular carcinoma cells." (PMID 25880358, 2015). "In 2015, it was shown that ERH regulates the DNA damage response in hepatocellular carcinoma." (PMID 30866868, 2019). "Another hypothesis was based on the observation that ERH is only weakly expressed in non-dividing cell lines of hepatocytes while it is abundantly expressed in fibroblast and hepatoma cell lines, suggesting that ERH might have a function necessary for normal cellular proliferation." (PMID 18500978, 2008).
colorectal cancer (2 papers, 2019 to 2023). A primary or metastatic malignant neoplasm that affects the colon or rectum. "In addition, ERH expression is inversely associated with the survival of colorectal cancer patients whose tumors harbor KRAS mutations." (PMID 30866868, 2019). "Analysis of changes in gene expression profile in colorectal cancer cells upon ERH depletion revealed the down-regulation of several additional cell cycle genes." (PMID 37254218, 2023).
lung carcinoma (2 papers, 2019 to 2021). "A predicted target site was detected in the 3′-untranslated region of the ERH gene, and transfected cells showed an interaction between the luciferase reporter containing the target sequences and miR-574-3p in lung cancer A549 cell lines." (PMID 30866868, 2019).
astrocytoma (1 paper, 2014). "In this study, we found that X-ray irradiation of cells from human lung adenocarcinoma, brain medulloblastoma, and astrocytoma induced the expression of miR-574-3p, which, in turn, suppressed the production of the enhancer of rudimentary homolog (ERH) protein and delayed cell growth." (PMID 24566139, 2014).
bladder urothelial carcinoma (1 paper, 2019). "This study aimed to determine whether the enhancer of the rudimentary homolog (ERH) gene regulates cell migration and invasion in human bladder urothelial carcinoma (BUC) T24 cells and the underlying mechanism." (PMID 30866868, 2019).
breast tumours (1 paper, 2008). "Consistently with the MTN results presented above, mean ERH expression in breast tumours was 2.5 fold more abundant than mean ERH expression in normal breast tissue (p = 0.1 according to two-tailed Mann-Whitney U-test)." (PMID 18500978, 2008).
Cirrhosis (1 paper, 2015). A chronic disorder of the liver in which liver tissue becomes scarred and is partially replaced by regenerative nodules and fibrotic tissue resulting in loss of liver function. "Similar to ATR, Chk1 mRNA expression is correlated with that of ERH (correlation coefficient = 0.504, p < 0.001), and Chk1 mRNA expression was higher in HCCs compared to normal tissues, cirrhosis tissue or dysplastic lesions." (PMID 25880358, 2015). "We further observed that ERH mRNA expression was significantly higher in HCCs (n = 35) than in normal tissues (n = 10), cirrhosis (n = 13) or dysplastic lesions (n = 17), indicating that the transition from premalignant lesions to small HCC is associated with an increase of ERH expression." (PMID 25880358, 2015).
colon carcinoma (1 paper, 2025). "To investigate whether loss of ERH abolishes ISG induction across species and cell types, we performed 3′ mRNA QuantSeq in IFNγ-treated or non-treated RKO-iCas9 cells (human colon carcinoma) and RAW 264.7-iCas9 cells (murine macrophage)." (PMID 40586312, 2025).
COVID-19 (1 paper, 2022). A disease caused by infection with severe acute respiratory syndrome coronavirus 2. "In this study, six co-upregulated genes, RPS7, IGF1R, DICER1, ERH, MCTS1, and TNPO1, and two co-downregulated genes, FLNA and PXN, were identified from COVID-19 and thrombosis datasets." (PMID 35692833, 2022). "Based on bioinformatics analysis and previous studies, this study identified hub genes (RPS7, IGF1R, DICER1, ERH, MCTS1, TNPO1, FLNA, and PXN) that may contribute to the evaluation and treatment of COVID-19 and thrombosis." (PMID 35692833, 2022).
invasive breast carcinoma (1 paper, 2008). A carcinoma that infiltrates the breast parenchyma. "ERH expression was further validated by real-time RT-PCR using the LightCycler® system in a set of formalin-fixed paraffin-embedded tissue specimens, consisting of 25 primary invasive breast cancers and 16 normal breast tissue samples." (PMID 18500978, 2008).
invasive ductal carcinoma (1 paper, 2008). "ERH was specifically and abundantly expressed in the tumour cells of invasive ductal carcinoma (D, G), while a less abundant ERH mRNA expression could be detected in the epithelial cells of normal breast lobuli (A)." (PMID 18500978, 2008).
metastatic tumors (1 paper, 2022). "They found that the ERH protein was downregulated in von Hippel-Lindau (VHL) tumors with Y98H mutation, but ERH expression was upregulated in many other metastatic tumors." (PMID 35677162, 2022).
prostate carcinoma (1 paper, 2024). A carcinoma that arises from epithelial cells of the prostate gland. "Gene set enrichment analysis revealed an association between DENND2D expression and the negative regulation of MYC target genes, including MAD2L1, ERH, and CLNS1A, which are overexpressed in prostate cancer and associated with poor survival." (PMID 39857609, 2024).
rhabdomyosarcoma (1 paper, 2019). A rare aggressive malignant mesenchymal neoplasm arising from skeletal muscle. "ERH also interacts with the H19 gene and regulates growth in nephroblasts, rhabdomyosarcomas and choriocarcinoma cells." (PMID 30866868, 2019).
urothelial carcinoma (1 paper, 2022). A malignant neoplasm derived from the transitional epithelium of the urinary tract (urinary bladder, ureter, urethra, or renal pelvis). "On the other hand, in the cancer model (LNCaP and PC-3), Menin was found to interact with the enhancer of the rudimentary homolog (ERH) transcription factor, recently reported to induce cell migration and invasion in urothelial carcinoma through c-myc activation." (PMID 34711954, 2022).
cancer (14 papers, 2008 to 2025). A tumor composed of atypical neoplastic, often pleomorphic cells that invade other tissues. "This is in agreement with the increased ERH expression level observed in cancers and the inhibition of cell proliferation in cancer cell lines by the silencing of ERH." (PMID 37887293, 2023). "Recently, more and more studies have shown that the expression of enhancer of rudimentary homolog (ERH) gene is closely related to cancers." (PMID 35677162, 2022). "In this review, we summarize and systematically introduce the ERH gene and its role in cancer cells." (PMID 35677162, 2022). "For the treatment of the majority of cancer patients, more targeted drugs to inhibit ERH expression should be developed." (PMID 35677162, 2022). "Accumulating studies have revealed that the enhancers of the rudimentary homolog (ERH) are involved in the occurrence and development of malignant tumors." (PMID 35774124, 2022). "The ERH gene plays an important role in the occurrence and development of malignant tumors, however, there are only a few drugs that target and regulate the expression of ERH by now." (PMID 35677162, 2022). "ERH is critically required for genomic stability and cancer cell survival by regulating cell cycle through its mRNA splicing activity." (PMID 34557456, 2021). "It mainly inhibits tumor progression by regulating the cell cycle, promoting cell apoptosis, and affecting DNA damage repair, and could be a good target for drug design for cancer such as ERH (Enhancer of Rudimentary Homolog)." (PMID 40313959, 2025). "ERH plays opposing roles in different tissue-specific cancers." (PMID 37430270, 2023). "(For more on the role of ERH in cancers, see the two reviews)." (PMID 37887293, 2023). "As ERH is a partner of dimerization co-factor of HNF-1 and which is involved in the cell development and regulation in many kinds of cancers, ERH may become a therapeutic target to inhibit the HNF-1 expression." (PMID 35677162, 2022). "These interactions suggest functions of ERH in cell growth, cancer, and DNA repair." (PMID 27830090, 2016). "We previously demonstrated that ERH is a novel splicing factor that regulates the mRNA splicing of the mitotic motor protein CENP-E, and knocking-down ERH in cancer cells resulted in chromosome congression defects during mitosis." (PMID 25880358, 2015). "There are many related studies on the role of ERH in cancer cells; however, there are none on tumor-targeted therapeutic drugs or related therapies based on the expression of ERH." (PMID 35677162, 2022). "Based on our finding that ERH is abundantly expressed in the majority of normal human tissues analyzed, it does not appear to be an ideal therapeutic drug target in human cancer treatment, but still such a role cannot be completely excluded." (PMID 18500978, 2008). "In addition, we found at the genetic level that ERH may inhibit apoptosis through regulating TLR, NF-κB, TNF or TGF-beta signaling pathways in human T24 cells to ultimately promote the growth of malignant tumors." (PMID 35774124, 2022).